ITPKC (inositol-trisphosphate 3-kinase C)
Description:
Catalyzes the phosphorylation of 1D-myo-inositol 1,4,5-trisphosphate (InsP3) into 1D-myo-inositol 1,3,4,5-tetrakisphosphate and participates to the regulation of calcium homeostasis. Can phosphorylate inositol 2,4,5-triphosphate to inositol 2,4,5,6-tetraphosphate (By similarity).
Synonyms: IP3KC; IP3-3KC
Tractability: PROTAC: ubiquitination databases record sites on it.
Gene: Protein-coding gene on chromosome 19 (40,717,112 to 40,740,860, forward strand). Ensembl gene ENSG00000086544.
Subcellular location: Nucleus; Cytoplasm
Subcellular location (Human Protein Atlas): Nuclear speckles
Pathways (Reactome):
Metabolism: Synthesis of IP3 and IP4 in the cytosol
Gene Ontology:
Molecular function: inositol-1,4,5-trisphosphate 3-kinase activity; inositol hexakisphosphate kinase activity; kinase activity
Biological process: cellular response to calcium ion; phosphatidylinositol phosphate biosynthetic process; inositol phosphate metabolic process; inositol phosphate biosynthetic process
Cellular component: cytoplasm; nuclear speck; nucleus; cytosol
Genetic constraint (gnomAD): Loss-of-function variants: 32 observed, 60.76 expected, observed/expected ratio (o/e) 0.53, 90% interval 0.4 to 0.71. The upper end of that interval is the gene's LOEUF score, 0.71, which puts it in group 2 of 6, group 1 being the genes least tolerant of losing a copy. Missense variants: 801 observed, 866.01 expected, observed/expected ratio (o/e) 0.92, 90% interval 0.87 to 0.98. Synonymous variants: 330 observed, 348.64 expected, observed/expected ratio (o/e) 0.95, 90% interval 0.86 to 1.04.
Homologues: Orthologues: chimpanzee ITPKC (99% identical), macaque ITPKC (97% identical), dog ITPKC (82% identical), pig ITPKC (82% identical), guinea pig ITPKC (79% identical), rabbit ITPKC (77% identical), mouse Itpkc (75% identical), rat Itpkc (72% identical), tropical clawed frog itpkc (35% identical), zebrafish itpkcb (35% identical), zebrafish itpkca (31% identical), Caenorhabditis elegans lfe-2 (22% identical), and 3 more. Paralogues in human: ITPKB (38% identical), ITPKA (31% identical), IP6K3 (11% identical), IP6K1 (11% identical), IP6K2 (10% identical), IPMK (10% identical).
Diseases named in the same sentence as ITPKC in open-access papers:
ITPKC is named in the same sentence as 25 diseases in open-access papers, as found by Europe PMC text mining. Sharing a sentence is not in itself a finding about the gene and the disease. The quoted sentences say what the papers report.
Kawasaki disease (13 papers, 2011 to 2025). A rare inflammatory disease characterized by an acute febrile, systemic, self-limiting, medium-vessel vasculitis primarily affecting children. "Overall, a deeper understanding of the biological processes involved is essential to substantiate the connection between ITPKC variants and Kawasaki Disease with experimental evidence." (PMID 40114120, 2025). "This study aims to conduct a comprehensive meta-analysis of existing research to define clear associations between variations in the ITPKC gene and the risk of developing Kawasaki disease (KD)." (PMID 40114120, 2025). "An ITPKC loss‐of‐function mutation has previously been found to be associated with the vascular autoimmune syndrome Kawasaki disease, indicating a possible link to inflammatory signaling and prompting us to investigate this gene further." (PMID 38991987, 2024). "Low activity of the mutated ITPKC gene in Kawasaki disease causes continuous phosphorylation of IP3, which binds to the IP3 receptor in the endoplasmic reticulum and causes calcium release into the cytoplasm." (PMID 36185934, 2022). "ITPKC (rs28493229) was confirmed to associate with the susceptibility of Kawasaki disease and CAL formation." (PMID 21533171, 2011). "For instance, PP3CC positively influences the protein level of ITPKC, a susceptibility gene of Kawasaki disease encoding a kinase that negatively regulates intracellular Ca2+ levels and inhibits the calcineurin-dependent activation of NFAT by phosphorylating IP3." (PMID 38791593, 2024). "ITPKC (rs28493229) C allele with Kawasaki disease was further confirmed in Taiwanese population." (PMID 23894522, 2013). "The most critical gene in the development of coronary artery lesions in Kawasaki disease is the discovery of the inositol 1,4,5-trisphosphate 3-kinase (ITPKC) gene." (PMID 36185934, 2022). "Inositol 1,4,5-trisphosphate 3-kinase C (ITPKC) is a negative regulator of T cell activation, and reduction in ITPKC function is known to promote Kawasaki disease." (PMID 32992708, 2020). "Genotypes of the SNPs of ITPKC (inositol 1,4,5-trisphosphate 3-kinase C) and BLK (B-lymphoid tyrosine kinase), which confer susceptibility to Kawasaki disease (KD)." (PMID 30592753, 2018). "Other reports have linked skipping of exon 9 of protein-tyrosine phosphatase sigma (PTPRS) to ulcerative colitis and reduced splicing efficiency of intron 1 of inositol 1,4,5-trisphosphate 3-kinase C (ITPKC) to Kawasaki disease." (PMID 28374191, 2017). "Regarding genetic factors, single nucleotide polymorphisms in ITPKC, CASP3, and TGF-beta pathways were reported to be associated with the development of Kawasaki disease in a Taiwanese population." (PMID 23864819, 2013). "Finally, taking into consideration the causal associated between ITPKC polymophisms and Kawasaki disease, we have noted that overexpression of ITPKC in lung fibroblasts results in enhanced T cell activation (ORAI1, STIM1), which is associated with Kawasaki disease." (PMID 38991987, 2024). "Inositol 1,4,5-trisphosphate 3-kinase C (ITPKC) gene is a negative regulator of T cell activation and is a proven promoter of Kawasaki disease." (PMID 32992708, 2020). "Haplotype frequencies of the ITPKC gene in patients with Kawasaki disease with or without coronary artery lesion formation." (PMID 24621571, 2014).
Calcium nephrolithiasis (2 papers, 2014 to 2018). The presence of calcium-containing calculi (stones) in the kidneys. "Recent studies found potential associations between ITPKC genetic variations and Hirschsprung disease, calcium nephrolithiasis, and cervical squamous cell carcinoma." (PMID 29780388, 2018). "In conclusion, we found that rs2607420 in the intron region of the ITPKC gene is associate with estimated creatinine clearance in patients with calcium nephrolithiasis." (PMID 24800221, 2014). "However, we cannot rule out the possibility that other low-frequency genetic polymorphisms of ITPKC may contribute to calcium nephrolithiasis." (PMID 24800221, 2014). "Our results indicated that rs2607420 CC genotype in the intron region of the ITPKC gene is associated with a lower eGFR by both Modification of Diet in Renal Diseases (P = 0.0405) and Cockcroft-Gault (P = 0.0215) equations in patients with calcium nephrolithiasis." (PMID 24800221, 2014).
kidney stone (2 papers, 2014 to 2021). "We investigated the association between calcium containing nephrolithiasis and genetic variants of ITPKC gene in Taiwanese patients." (PMID 24800221, 2014). "The purpose of this study was to determine whether SNPs (rs11673492, rs28493229, rs7257602, rs7251246, rs890934, rs10420685, rs2607420, and rs2290692) of ITPKC are associated with the recurrence, stone number, or kidney function of patients with nephrolithiasis." (PMID 24800221, 2014).
thrombosis (2 papers, 2023 to 2025). "In children with CAA who experienced thrombosis, ITPKC mRNA levels were decreased." (PMID 40114120, 2025). "ITPKC mRNA levels were lower in children with CAA who developed thrombosis (P=0.039)." (PMID 37404818, 2023). "Notably, the mRNA levels of ITPKC were significantly lower in children with CAA who developed thrombosis than in those without thrombosis (0.34 vs. 0.45, P = 0.039)." (PMID 37404818, 2023).
triple-negative breast carcinoma (2 papers, 2020 to 2024). An invasive breast carcinoma which is negative for expression of estrogen receptor (ER), progesterone receptor (PR), and human epidermal growth factor receptor 2 (HER2). "ITPKC expression was highest in triple negative breast cancer, associated with its survival, and was its independent prognostic factor." (PMID 32992708, 2020). "Furthermore, ITPKC over-expression in triple-negative breast cancer was associated with reduced disease-free survival and poor prognosis." (PMID 39272711, 2024).
aneurysm (1 paper, 2011). Bulging or ballooning in an area of an artery secondary to arterial wall weakening. "Our results indicated that C allele of ITPKC rs28493229 had significant higher risk to have aneurysm formation." (PMID 21533171, 2011). "Taken together, our results indicated that C-allele of ITPKC SNP rs28493229 is associated with the susceptibility and aneurysm formation in KD patients in a Taiwanese population." (PMID 21533171, 2011). "Importantly, KD patients carry ITPKC rs28493229 C allele had significant higher risk to have aneurysm formation." (PMID 21533171, 2011). "SNP rs28493229 of ITPKC was associated with the KD patients with aneurysm formation." (PMID 21533171, 2011).
breast carcinoma (1 paper, 2020). "We were unable to find any study other than ours to report the association of ITPKC expression with cell proliferation in breast cancer." (PMID 32992708, 2020). "We studied whether ITPKC expression is associated with clinical aggressiveness of breast cancer in The Cancer Genome Atlas (TCGA) cohort." (PMID 32992708, 2020). "Given the role of tumor infiltrating lymphocytes in NAC and since TNBC has the most abundant immune cell infiltration in breast cancer, we hypothesized that the ITPKC expression level is associated with NAC response and prognosis in TNBC." (PMID 32992708, 2020). "The ITPKC gene was highly expressed in the breast mammary gland, but its expression was found to be highest in breast cancer cells among other stromal cells in a bulk tumor." (PMID 32992708, 2020). "ITPKC was significantly expressed higher in breast cancer cells compared with stroma or immune cells." (PMID 32992708, 2020). "Given the critical role of immune response in breast cancer, we aimed to determine the clinical relevance of ITPKC expression in breast cancer." (PMID 32992708, 2020). "The ITPKC gene was expressed in the mammary gland, but its expression was highest in breast cancer cells among other stromal cells in a bulk tumor." (PMID 32992708, 2020). "In order to identify which cells express ITPKC within a bulk breast cancer tumor, we analyzed ITPKC expression in tumor cells, B cells, stromal cells, myeloid cells and T cells using single-cell sequencing data of primary breast cancer (GSE75688) utilizing the same method we previously reported." (PMID 32992708, 2020).
cervical cancer (1 paper, 2020). A primary or metastatic malignant neoplasm involving the cervix. "Recently, ITPKC expression was linked with cervical cancer carcinogenesis." (PMID 32992708, 2020).
colon cancer (1 paper, 2020). "Overexpression of ITPKC was shown to increase microvascular adhesion of circulating colon cancer cells before hepatic metastasis formation." (PMID 32992708, 2020). "Using random homozygous gene perturbation (RHGP) in combination with specific adhesion assays of cancer cells, expression changes of ITPKC were found to regulate hepatic microvascular adhesion of circulating colon cancer cells by overexpression in nonadherent cancer cell clones." (PMID 32992708, 2020).
colorectal cancer (1 paper, 2024). A primary or metastatic malignant neoplasm that affects the colon or rectum. "ITPKC overexpression is associated with an increased risk of liver metastasis in colorectal cancer." (PMID 39272711, 2024).
Erythema (1 paper, 2025). Redness of the skin, caused by hyperemia of the capillaries in the lower layers of the skin. "Furthermore, interactions between ITPKC polymorphisms, including rs10420685, and other genes like solute carrier 11a1 (SLC11A1) have been found to influence the risk of KD and the erythema of the BCG injection site." (PMID 40114120, 2025).
glioblastoma (1 paper, 2022). The most malignant astrocytic tumor (WHO grade IV). "Although OGFOD1, C1RL, CD81, and ITPKC play pivotal roles in several cancers, their involvement in glioblastoma remains undocumented." (PMID 35936722, 2022).
lung carcinoma (1 paper, 2015). "For lung cancer, we found 3 SNPs across three inositol phosphate metabolism genes with P < 0.001, including rs13021302 (INPP5D), rs11083841 (CALM3), and rs11668501 (ITPKC)." (PMID 25683757, 2015).
osteoporosis (1 paper, 2018). A condition of reduced bone mass, with decreased cortical thickness and a decrease in the number and size of the trabeculae of cancellous bone (but normal chemical composition), resulting in increased fracture incidence. "Although several bioinformatics tools have allowed us to understand the potential functions of ITPKC polymorphisms in determining the risk of osteoporosis, functional studies on animal models in relevant tissues are still needed to clarify the underlying mechanisms." (PMID 30355649, 2018).
cancer (2 papers, 2020 to 2022). A tumor composed of atypical neoplastic, often pleomorphic cells that invade other tissues. "Given that ITPKC is a negative regulator of T cells, we hypothesized that a low level of ITPKC expression is associated with enhanced cancer immunity, thus is associated with better response to NAC and survival in TNBC." (PMID 32992708, 2020). "In the univariate analysis of disease-specific survival (DSS) in the TCGA cohort, AJCC cancer staging categories T, N and M, and ITPKC expression level had a significant hazard ratio (HR)." (PMID 32992708, 2020).
ITPKC also shares sentences with these, for which no sentence is quoted: cervical squamous cell carcinoma (2 papers); breast invasive carcinoma (1); Breast Tumor (1); coronary artery aneurysms (1); hepatocellular carcinoma (1); Hirschsprung disease (1); Renal Diseases (1); systemic vasculitis (1); tumor (1); ulcerative colitis (1).